INS (insulin)
Diseases named in the same sentence as INS in open-access papers (continued):
Sharing a sentence is not in itself a finding about the gene and the disease.
diabetes (continued). "The difference between the two types of diabetes is interesting and supports a possible functional importance of betatrophin in T2D, where it could be playing a role in compensating for the increased insulin demand." (PMID 26077345, 2015). "One could argue that we were not able to fully control for diabetes duration and other cofounders, which results in a much higher risk of SHEs attributable to human insulin." (PMID 26458540, 2015). "We speculate that this relative lack of α-cells might preserve the functional balance of insulin to glucagon after ongoing β-cell loss and thereby protect dogs from clinical presentation until late in the course of diabetes." (PMID 26057531, 2015). "Once GSK-3β could be considered as a potential therapeutic target for diabetes and neurological disorders due to its role in insulin pathway substrates and inflammation process, western blot assays were performed to verify the presence of some age related changes in AKT and GSK-3β activity." (PMID 26647069, 2015). "On the other hand, type 2 diabetes mellitus (T2DM), which accounts for over 90% of patients with diabetes, occurs through mechanisms such as insulin resistance in peripheral tissues and increased blood glucose levels induced by overnutrition associated with the deficiency of insulin secretion." (PMID 26075247, 2015). "If the pattern of glucose excursion is favored of type 1 diabetes mellitus (DM), the titration of insulin dose in these patients should be more careful than in those with type 2 DM to avoid hypoglycemia." (PMID 25621692, 2015). "Therefore, even in non-obese (BMI <30 kg/m2) Asians, we suggest that the impact of lifestyle intervention on the onset of type 2 diabetes mellitus is larger among subjects with high BMI than among those with low BMI when impaired insulin secretion capacity is suspected." (PMID 26005064, 2015). "Diabetes mellitus could be defined as a metabolic disorder of multiple etiology characterized by chronic hyperglycemia with disturbances of carbohydrate, fat and protein metabolism resulting from defects in insulin secretion, insulin action, or both." (PMID 26362065, 2015). "Therefore, chronic alterations of insulin/IGF1 levels (or biological activity) because of systemic metabolic dysfunction like in obesity or diabetes are likely to create an environment in which cancer cells that depend on these factors thrive particularly well." (PMID 26284118, 2015). "However, the levels of intracellular glycogen deposition were reduced in diabetes because of diminished insulin activity, as insulin facilitates intracellular glycogen storage by inhibiting the activity of glycogen phosphorylase and stimulating the activity of glycogen synthase." (PMID 26783461, 2015). "Findings from in vitro and animal studies indicate that inorganic nitrate/nitrite could be considered as an alternative source of endogenous NO which could enhance the insulin signaling pathway, glucose uptake and attenuate insulin resistance and diabetes complications." (PMID 25991919, 2015). "However, islet β-cell hyperplasia is not necessarily associated with increased insulin release to compensate for increased insulin demand after overt diabetes." (PMID 29124161, 2015). "Thus, a reduced capacity of insulin secretion is typical of East Asians, which could render them sensitive to the development of diabetes in conditions of over-nutrition." (PMID 25944304, 2015). "However, as might be expected, the most common endocrine abnormality was diabetes mellitus; five of the nine patients with abnormal glucose tolerance tests required insulin." (PMID 25352051, 2015). "Considering the dual roles played by IL-6 on insulin sensitivity in diverse tissues and that these effects depend on different times of exposition and signaling pathways, further studies are necessary to ensure the safety of blocking IL-6 pathways as a pharmacological target to treat diabetes." (PMID 26578976, 2015).
diabetes (continued). "For example, patients with diabetes mellitus requiring insulin can personalize the dose, frequency, and timing of insulin therapy based on blood glucose readings, in conjunction with selection of the appropriate insulin formulation(s) for their insulin regimen." (PMID 25950758, 2015). "It however remains unclear what the association is of ‘normal’ glucose and insulin (glucose and insulin levels within the population reference range), with macro- and micro-structural brain changes in older persons without diabetes." (PMID 26178969, 2015). "Diabetes mellitus (DM) is a multifactorial metabolic disorder, characterized by hyperglycemia, resulting from abnormalities in insulin secretion, insulin action, or both." (PMID 25928419, 2015). "Furthermore, deletion of other genes in osteoblasts in mice led to pancreatic β cell proliferation, a rise in insulin secretion and sensitivity that protected against obesity and diabetes, demonstrating at least the capacity of osteoblasts to contribute to energy metabolism." (PMID 26407553, 2015). "This suggests that insulin sensitivity may have been reduced by cardiac autonomic dysfunction more than by obesity in our subjects, despite obesity being considered a more important factor for the initial development of diabetes or metabolic syndrome." (PMID 26277879, 2015). "It is noteworthy that Improvement of insulin sensitivity by means of weight loss may not be enough to induce the remission of diabetes if there is advanced destruction of beta cells." (PMID 26185747, 2015). "Taken together, these data suggest a requirement for IRE1α and XBP1 in many processes that affect glucose-mediated stimulation of insulin production by β cells—a finding that could strongly impact efforts to target this pathway for treatment of diabetes mellitus." (PMID 26469794, 2015). "Patients may ultimately require insulin replacement therapy to adequately manage their diabetes." (PMID 26053004, 2015). "Type 2 Diabetes Mellitus (T2DM) is a chronic degenerative disease characterized by alterations in the metabolism of lipids, carbohydrates and proteins and is caused by a decrease in insulin secretion, target-tissue resistance and increased hepatic glucose output." (PMID 25859777, 2015). "Diabetes mellitus is a chronic metabolic disease, characterized by a disorder in the metabolism of carbohydrates, lipids, and amino acids, either as a result of decreased insulin secretion or due to a reduction to insulin sensitivity of the cells of the body cells." (PMID 25789172, 2015). "Additionally, diabetes is associated with high levels of blood cytokines including IL-1β, IL-6, IL-12, IL-17, IL-18, TNF-α and IFN-γ, which mediate the physiological adaption of insulin production and insulin resistance." (PMID 26684748, 2015). "Although hypoglycemia in patients with diabetes is mostly iatrogenic and is mainly caused by glucose-lowering agents, such as insulin and sulfonylureas, hypoglycemia in patients without diabetes can be caused by many factors including malnutrition, alcohol abuse, hepatic failure, and sepsis." (PMID 25192953, 2015). "Diabetes mellitus (DM) is a common, chronic, metabolic syndrome characterized by hyperglycemia, resulting from defects in insulin secretion, insulin effects, or both." (PMID 26229969, 2015). "Because excessive insulin and IGF-1 signaling by hyperinsulinemia may be one of the most important causes of the development and proliferation of cancer, exogenous insulin is a suspected powerful carcinogenetic factor in diabetes patients." (PMID 25866823, 2015). "Interestingly, this patient was also treated by insulin for diabetes." (PMID 26277098, 2015). "People who develop diabetes usually pass through the phases of excessive adipogenesis (obesity), insulin resistance, hyperinsulinemia, pancreatic beta cells stress, and damage leading to progressive decrease of insulin secretion, impaired glucose postprandial, and fasting levels." (PMID 26464869, 2015).
diabetes (continued). "The Ghanaian men had the lowest mean insulin and leptin levels (79.8 ± 28.1 pmol/L and 4.9 ± 6.3 μg/L, respectively), while the US men had the highest insulin, leptin, as well as percentage participants with diabetes (138.0 ± 91.4 pmol/L, 11.2 ± 13.4 μg/L, and 6.7 %, respectively)." (PMID 26374293, 2015). "Major barriers cited by focus group participants and key informants to effectively managing diabetes were lack of resources such as testing supplies, insulin, medication, and lack of knowledge regarding causation of the disease and how to prevent complications." (PMID 27175439, 2015). "Availability of continuous measures of glucose and insulin concentrations in the mothers also enabled us to test whether glucose and insulin concentrations in the absence of diabetes are associated with stress responses in the offspring." (PMID 25478935, 2015). "Diabetes mellitus (DM) is a metabolic disorder resulting from a defect in insulin secretion, insulin action, or both leading to chronic hyperglycemia." (PMID 26469405, 2015). "While the glucose disposal profile still remained insulin resistant relative to lean volunteers, the improvement was clinically meaningful as it was accompanied by normalisation of fasting plasma glucose and HbA1c, and cessation of diabetes medication in all four of the volunteers with diabetes." (PMID 25876175, 2015). "Furthermore, active component (SalB) from Dan-Shen can exhibit antidiabetic activity and inhibit symptoms of diabetes mellitus in rats and these effects may partially be correlated with its insulin sensitivity, glycogen synthesis and antioxidant activities." (PMID 26699542, 2015). "Thus, vglycin may represent a new therapeutic agent for preventing and treating diabetes by replenishing endogenous insulin-positive cells." (PMID 26510947, 2015). "Therefore, the use of insulin might be a marker for more severe diabetes or obesity, which could be the real factors affecting breast cancer mortality." (PMID 26171401, 2015). "Diabetes mellitus (DM) remains the world's most common metabolic disorder resulting from defects in insulin secretion and/or action." (PMID 26246844, 2015). "Therefore, levels of GA and insulin were selected as the key indexes of diabetes in this study." (PMID 26221177, 2015). "However, hyperglycemia and hyperinsulinemia may exist rarely in patients with preexisting diabetes because blood glucose levels are usually controlled well using oral hypoglycemic agents or insulin." (PMID 25854171, 2015). "In conclusion, the add-on of GLP-1 analogue to the intensive insulin therapy with CSII not only significantly showed further effect among glucose control but remarkably potentiated the β- cell function in patients with poorly controlled type 2 diabetes mellitus." (PMID 26607841, 2015). "Diabetes mellitus (DM) is a metabolic disorder characterized by hyperglycemia resulting from defect either of secretion or action of endogenous insulin." (PMID 25789083, 2015). "Taken together, these studies support the idea that SD has pronounced effects on insulin sensitivity, but in a chronic setting, may also lead to impaired insulin secretion, both of which could be contributing factors in the onset of diabetes and metabolic syndrome in humans." (PMID 24102714, 2014). "However, this study did not evaluate the association of OM adipocyte size with insulin sensitivity and risk of development of diabetes mellitus." (PMID 25251402, 2014). "Diabetes mellitus (DM) is a metabolic disorder resulting from a defect in insulin production, impaired insulin action or both." (PMID 24990684, 2014). "Thus, insulin could have a global effect on the control of various diseases ranging from hypertension and diabetes mellitus to coronary artery disease." (PMID 24649391, 2014).
diabetes (continued). "Type 1 diabetes is insulin-dependent diabetes mellitus caused by absolute deficiency of insulin secretion while type 2 diabetes (T2DM) is non-insulin-dependent diabetes mellitus caused by both inadequate insulin secretion and insulin resistance of target organs." (PMID 25580119, 2014). "Due to the progressive nature of the disease, most patients with type 2 diabetes mellitus (DM) ultimately fail on oral glucose-lowering drugs and therefore require insulin therapy." (PMID 25175981, 2014). "EA combined with the oral insulin sensitizer rosiglitazone improved insulin sensitivity in rats and humans with type II diabetes mellitus (DM)." (PMID 25024728, 2014). "Consequently, insulin secretion is collapsed and mice have developed diabetes." (PMID 24672804, 2014). "Also diabetes is associated with disturbances in carbohydrate, protein and fat metabolism which occur secondary to an absolute or relative lack of insulin (hypoinsulinemia)." (PMID 23579248, 2014). "Numeracy is particularly important to patients with diabetes because diabetes requires self-management skills that rely on mathematics such as counting carbohydrates, interpreting glucose monitoring, applying a sliding scale for insulin, and calculating insulin doses based on carbohydrate intake." (PMID 25527255, 2014). "Therefore, they are called insulin-sensitizing medications used in the treatment of diabetes." (PMID 24524207, 2014). "This analysis demonstrated that metformin use may reduce lung cancer risk in patients with diabetes but not in a smoking-adjusted subgroup and that insulin use may be associated with an increased lung cancer risk in subjects with diabetes." (PMID 24924771, 2014). "In addition to the beneficial effects of NO-mediated vasodilation on blood pressure homeostasis, several studies suggest that optimal stimulation of PI3 kinase-Akt-NO pathway is critical for the various protective effects of insulin signaling that are impaired or completely inhibited in diabetes." (PMID 25100328, 2014). "A recent meta-analysis suggested that higher dietary magnesium intake was inversely associated with fasting glucose and fasting insulin in individuals free of diabetes, generally, irrespective of genetic variation at the glycemia and magnesium-related loci investigated." (PMID 25533010, 2014). "Besides, the association with diabetes duration is not linear and there is a general decrease in quality of life during the initial years of the disease that smoothes and reverts for patients with a long duration of diabetes, especially those with insulin therapy." (PMID 25138117, 2014). "Insulin treatment might suggest more severe and advanced diabetes in this cohort." (PMID 24447406, 2014). "The comorbidities such as nephropathy and urinary tract diseases should always be considered for adjustment, because these are important risk factors for bladder cancer and are commonly seen in the diabetic patients who may have a long duration of diabetes and happen to use insulin." (PMID 24466131, 2014). "Additionally, the duration of diabetes, the insulin injection, and the level of hyperglycemic control may also correlate with depression." (PMID 24868316, 2014). "It follows that the ideal approach to treating diabetes in pregnancy necessarily includes frequent blood glucose self-monitoring, adequate dietary guidelines that take the mother's initial weight and the various stages of gestation into account, and appropriate insulin therapy where necessary." (PMID 25295059, 2014). "However, one should be cautious in making direct conclusions from these epidemiological studies, as it might be because the patients were having a more severe stage of diabetes that they required treatment with insulin." (PMID 24574966, 2014). "Diabetes mellitus (DM) is a chronic metabolic disorder in the endocrine system resulting from defects of insulin secretion (type 1), increased cellular resistance to insulin (type 2), or both." (PMID 25243114, 2014).
diabetes (continued). "Although the mechanism underlying the increase in new onset T2DM in patients treated with statins is unknown, it is possible that statins interfere with insulin signaling, leading to hyperinsulinemia, insulin resistance, metabolic syndrome, pre-diabetes and diabetes." (PMID 24655568, 2014). "Finally, another potential interference could stem from diabetes drugs that modulate body weight, such as insulin, sulfonylureas, and metformin." (PMID 24678928, 2014). "Elevated iron stores may induce diabetes through a variety of mechanisms, including oxidative damage to pancreatic β cells, impairment of hepatic insulin extraction by the liver, and interference with insulin's ability to suppress hepatic glucose production." (PMID 25162051, 2014). "Insulin treatment may attenuate the impairment of Bcrp expression and function induced by diabetes." (PMID 25540622, 2014). "Hence, investigating the association between genetic loci linked with either HbA1c or gluco- and lipotoxic properties and time to redemption of 1st drug and 1st insulin prescription may also reveal links to diabetes progression." (PMID 25157406, 2014). "However, the insulin treatment group included individuals with both types of diabetes." (PMID 25475416, 2014). "Exendin-4 is a peptide similar to glucagon that promotes insulin gene transcription, synthesis and secretion, inhibits the apoptosis of pancreatic β-cells at the gene level, promoting their proliferation and regeneration, and reverses the development of diabetes." (PMID 25302615, 2014). "Furthermore, its modified expression in pancreatic cells may alter insulin folding and adiponectin response, which may be a new etiology for diabetes." (PMID 25526565, 2014). "This study therefore points out that subtle increase in physiological ROS production, particularly in muscle, might reflect the contribution of ROS to insulin sensitivity early in the development of insulin resistance, prior to the onset of hyperglycemia/hyperlipidemia and frank diabetes." (PMID 25143800, 2014). "Whilst there may be many reasons for a decline in management of diabetes and its complications in young adults using insulin pumps, one might be that stretched diabetes teams lack adequate specialist resources to provide the more complex and time consuming support needed to optimise results." (PMID 24884679, 2014). "It reduces the metabolic adaptation to insulin action, and forces amino acids to be used as energy substrates thus reducing the need to burn lipids and carbohydrates which may promote insulin resistance and diabetes by their glucotoxicity and lipotoxicity." (PMID 25106484, 2014). "a) Non adherence to prescribed treatment regimen: Factors found to be significantly associated with non-adherence were cost of insulin, occupation of respondent’s mother, family history of diabetes, poor understanding of prescription, irregularity of follow up, and fear of insulin." (PMID 24772118, 2014). "This interaction between insulin resistance, cognitive dysfunction and positive effects of insulin administration on memory performance prompted some to suggest that Alzheimer’s disease could be considered a form of diabetes mellitus of the brain." (PMID 24941010, 2014). "In addition, the glucose level, diabetes mellitus, insulin treatment and obesity may affect FDG biodistribution and SUV measurements and thus limit the clinical application of the present study." (PMID 24642729, 2014). "Also in Venezuelan subjects, previous studies have shown that the coexistence of obesity and family history of diabetes may be responsible for the deficit of pancreatic insulin secretion." (PMID 24699193, 2014). "Insulin producing beta cell and glucagon producing alpha cells are colocalized in pancreatic islets in an arrangement that facilitates the coordinated release of the two principal hormones that regulate glucose homeostasis and prevent both hypoglycemia and diabetes." (PMID 25051960, 2014).